FCAR (Fc alpha receptor)
Description:
Binds to the Fc region of immunoglobulins alpha. Mediates several functions including cytokine production.
Synonyms: CD89; FcalphaRI; FcalphaR; CTB-61M7.2
Tractability: Small molecule: a structure with a bound ligand is known; it has a high-quality binding pocket. Antibody: its Gene Ontology location is reachable by antibodies, with high confidence; UniProt places it where antibodies can reach, with medium confidence; UniProt predicts a signal peptide or a membrane-spanning region; the Human Protein Atlas places it where antibodies can reach.
Gene: Protein-coding gene on chromosome 19 (54,874,235 to 54,891,420, forward strand). Ensembl gene ENSG00000186431.
Subcellular location: [Isoform A; 1]: Cell membrane; 2]: Cell membrane; 3]: Cell membrane; Secreted (Isoform B); Secreted (Isoform B-delta-S2)
Subcellular location (Human Protein Atlas): Plasma membrane
Pathways (Reactome):
Immune System: Neutrophil degranulation
Gene Ontology:
Molecular function: protein binding; immune receptor activity; transmembrane signaling receptor activity
Biological process: immune response; immune response-inhibiting cell surface receptor signaling pathway
Cellular component: plasma membrane; ficolin-1-rich granule membrane; specific granule membrane; tertiary granule membrane; extracellular region
Genetic constraint (gnomAD): Loss-of-function variants: 27 observed, 33.16 expected, observed/expected ratio (o/e) 0.81, 90% interval 0.6 to 1.12. The upper end of that interval is the gene's LOEUF score, 1.12, which puts it in group 4 of 6, group 1 being the genes least tolerant of losing a copy. Missense variants: 404 observed, 373.98 expected, observed/expected ratio (o/e) 1.08, 90% interval 1 to 1.17. Synonymous variants: 134 observed, 142.08 expected, observed/expected ratio (o/e) 0.94, 90% interval 0.82 to 1.09.
Homologues: Orthologues: chimpanzee FCAR (97% identical), chimpanzee FCAR (95% identical), macaque FCAR (86% identical), pig FCAR (53% identical). Paralogues in human: NCR1 (36% identical), LILRA2 (36% identical), LILRA4 (34% identical), LILRA5 (34% identical), LILRA1 (34% identical), GP6 (33% identical), LILRA6 (33% identical), LILRB1 (33% identical), LILRB2 (33% identical), LILRB3 (33% identical), IGSF1 (30% identical), LILRB5 (29% identical), and 13 more.
Diseases named in the same sentence as FCAR in open-access papers:
FCAR is named in the same sentence as 56 diseases in open-access papers, as found by Europe PMC text mining. Sharing a sentence is not in itself a finding about the gene and the disease. The quoted sentences say what the papers report.
Sepsis (7 papers, 2019 to 2025). Sepsis is defined as life-threatening organ dysfunction caused by a dysregulated host response to infection. "Together, we illustrated by machine learning that CYBB and FCAR were significantly associated with sepsis-related mortality." (PMID 37901228, 2023). "In particular, CYBB and FCAR were significantly associated with survival in patients with sepsis, and both genes were validated using animal experiments and analysis of clinical specimens." (PMID 37901228, 2023). "Our findings implied that higher CYBB and FCAR expression were significantly and positively associated with higher mortality rates in the sepsis group." (PMID 37901228, 2023). "The upregulation of FCAR in certain cohorts strongly distinguished sepsis patients from healthy controls, highlighting its potential as both a diagnostic biomarker and a therapeutic target." (PMID 40665987, 2025). "In the case of these samples, a pattern consisting of upregulation of CKAP4 and FCAR along with downregulation of RNF4 decisively discriminates between sepsis patients and healthy samples." (PMID 40665987, 2025). "Bioinformatics analysis showed that CYBB and FCAR levels are related to the survival of patients with sepsis." (PMID 37901228, 2023). "CYBB and FCAR levels were significantly elevated in sepsis patients compared with the healthy group." (PMID 37901228, 2023). "FCAR, a typical innate receptor for bacteria, is suggested to be an important protector against sepsis through mediation of bacterial phagocytosis." (PMID 32174955, 2020). "CYBB and FCAR may be reliable biomarkers of survival in patients with sepsis, as well as potential targets for sepsis treatment." (PMID 37901228, 2023). "Several previous studies have linked FCAR and CYBB to sepsis." (PMID 37901228, 2023). "Of these, CYBB and FCAR were independent predictors of poor survival in patients with sepsis." (PMID 37901228, 2023). "In addition, FCAR gene expression levels were significantly elevated in patients with sepsis, which may play as a potential biomarker for the diagnosis of sepsis and be involved in the formation of neutrophil extracellular traps (NETs)." (PMID 40630623, 2025). "Overall, we report that a change in CKAP4, FCAR, and RNF4 expression patterns is a key feature of sepsis on the genomic level." (PMID 40665987, 2025). "Our analysis highlights CKAP4, FCAR, and RNF4 as key genetic drivers in sepsis-related variations." (PMID 40665987, 2025). "We hypothesize that the variations in gene expression in sepsis patients occur in specific cells in the blood and then reflect a pattern of upregulation of genes CKAP4 and FCAR in whole blood samples along with downregulation of RNF4." (PMID 40665987, 2025). "Using our new plasma data (11 septic shock samples and 21 sepsis samples), the combinations of five genes (NONO, CKAP4, FCAR, PLEKHO1, BMP6) reached an overall accuracy of 93.75%, with a sensitivity of 81.82% and a specificity of 100.00%." (PMID 40665987, 2025). "While literature links NONO, FCAR, BMP6, RNF4, and RNASE2 to sepsis or Systemic Inflammatory Response Syndrome (SIRS), their interactions and the roles of PLEKHO1, OGFOD3, and CKAP4 in sepsis are less documented." (PMID 40665987, 2025).
asthma (3 papers, 2019 to 2023). "On the other hand, in asthma it is believed that the activation of granulocytes represents a driving force, since Fc alpha receptor (FcαR) is widely distributed in granulocytes." (PMID 34557509, 2021). "Accumulating evidence shows that ITGB4, SEMA3D, FCAR (Fc fragment of IgA receptor), KIT (KIT proto-oncogene, receptor tyrosine kinase), PGLYRP1, IL17RB, BIRC5 and PTGS1 are associated with prognosis in asthma." (PMID 36837510, 2023).
atherosclerosis (3 papers, 2012 to 2020). A disease characterized by the build-up of fatty material and calcium deposition in the arterial wall resulting in partial or complete occlusion of the arterial lumen. "Several of the differentially regulated genes are involved in vascular pathophysiology; for example: DNAJB6 and DUSP1 (atherosclerosis), NAMPT (vascular inflammation), FCAR (myocardial infarction), IL8 (vascular remodelling), FFAR2 (lipid metabolism) and SOD2 (idiopathic cardiomyopathy (IDC))." (PMID 22409835, 2012).
viral infections (3 papers, 2018 to 2021). "They neutralize viral infection of respiratory epithelial cells via extracellular and intracellular immune exclusion and also exhibit FcαR-mediated effector functions." (PMID 34868036, 2021).
COVID-19 (2 papers, 2022). A disease caused by infection with severe acute respiratory syndrome coronavirus 2. "These antibodies might rather contribute via their interaction with FcαR on innate immune cells to this long-lasting severe COVID-19 state." (PMID 36248831, 2022). "Here, we report the absence of FcαR or FcγRII-mediated ADE resulting from the polyclonal antibody responses identified in units of CCP used as therapy for severe and life-threatening COVID-19." (PMID 35259162, 2022).
leukemia (2 papers, 2022 to 2024). A malignant (clonal) hematologic disorder, involving hematopoietic stem cells and characterized by the presence of primitive or atypical myeloid or lymphoid cells in the bone marrow and the blood. "Finally, we detected the expression of marker genes of macrophage and NK cells, and found that five genes of FCAR, FCGR3A, PREX1, S100A8 and S100A9 all were significantly overexpressed in the leukemia cells of HAP1 compared with that in the normal stroma cells of HS-5 (p < 0.05)." (PMID 39583114, 2024).
malaria (2 papers, 2011 to 2013). Malaria is a serious and sometimes fatal disease caused by a parasite that commonly infects a certain type of mosquito which feeds on humans. "Gene expression levels were greater than two-fold change in acute febrile malaria including: Fc alpha receptor, Fc gamma receptor 3B, Fc epsilon receptor 1G, PI3K, MAP2K2, Arf6, KLRC3, KIR3DL2, and CEBP gamma (range two- to four-fold)." (PMID 24188121, 2013).
shigellosis (2 papers, 2025). Shigellosis is a bacterial infection leading to dysentery and is caused by Shigella, which are small, ubiquitous Gram-negative bacteria belonging to the enterobacteria family. "On the other hand, S. flexneri 2a OPS IgA-dependent binding to FcαR and neutrophil phagocytosis were associated with resistance to shigellosis within 90 days in a high Shigella burden (military) area in Peru." (PMID 40237475, 2025). "Notably, we have recently shown that Shigella OSP-specific IgA responses, which bind and activate polymorphonuclear cells via Fc alpha receptor (FcαR), are associated with protection against incident shigellosis in humans in Peru in a high-burden and resource-limited setting." (PMID 40763727, 2025).
autoimmune disease (1 paper, 2020). A disorder resulting from loss of function or tissue destruction of an organ or multiple organs, arising from humoral or cellular immune responses of the individual to their own tissue constituents. "Therefore, the downregulation of FCAR reported in this study may indicate that NCWS shares some pathological features with autoimmune diseases." (PMID 32183058, 2020).
coronary artery disease (1 paper, 2020). "The variation in FCAR which causes an amino acid alteration was found to increase the risk of MI and coronary heart disease, indicating the potential functional role of FCAR in the development of cardiovascular disease." (PMID 32581823, 2020).
dengue (1 paper, 2023). "While these data suggest that DENV-elicited inflammation is unlikely to increase the susceptibility of circulating monocytes to IgA-mediated ADE during primary dengue by increased FcαR expression, ADE is a feature associated with heterologous secondary DENV infections." (PMID 37639455, 2023).
ischemic stroke (1 paper, 2025). A stroke disorder caused by obstruction of blood flow to the brain, due to thrombotic (local blood clot formation) or embolic (due to a blood clot or other material traveling from another site) event. "All four biomarkers (SRC, TLR8, FCAR, and HIF1A) were significantly upregulated in ischemic stroke patients compared to healthy controls." (PMID 40948644, 2025).
peripheral artery disease (1 paper, 2020). "Several genes were previously shown upregulated in circulating leukocytes in patients with peripheral artery disease (FCAR, FFAR2, DUSP5, PLAUR)." (PMID 31875423, 2020).
vasculitis (1 paper, 2024). "Additionally, genes such as LILRB1 and Fc alpha receptor (CD89) have also been reported to play a role in immune response as vasculitis." (PMID 38361743, 2024).
tumor (19 papers, 2011 to 2025). "There is considerable research demonstrating that cross-linking of FcαR (CD89) using bispecific antibodies can induce tumor cytotoxicity, as well as target pathogens, such as Streptococcus pneumonia, Porphyromonas gingivalis, and Bordetella pertussis." (PMID 27419146, 2016). "For instance, a recombinant single chain Fv fragment specific for HLA class II, on the tumor cell, and for the IgA Fc receptor (FcαR or CD89) on PMNs [(FcαRI × HLA class II) bsscFv] has recently been engineered and tested in the context of B-cell malignancies." (PMID 24212958, 2011). "In this study we thoroughly characterized previously unknown features of this model, such as the integration site of the FCAR gene, CD89 expression in healthy and tumor-bearing mice, expression of myeloid activation markers and FcγRs and tumor killing capacity." (PMID 37338671, 2023). "We identified six cell types, including macrophages (PPP1R17), monocytes and neutrophils (FCAR, S100A12, CD93), tumor stem cells (CPZ), smooth muscle cell populations and epithelial cells (CSF3, TTC23L)." (PMID 41049004, 2025). "Rather, the colonic CD14+CD163− MNPs display Mo-like morphology, share gene expression with monocytes (FCAR/CD89 and C5AR1/CD88), and are molecularly and functionally distinct from the CD14brightCD163+ Mɸ subset detected in inflamed IBD mucosa, RA synovial fluid, and tumor ascites." (PMID 32230977, 2020).
infection (16 papers, 2016 to 2025). The state of being infected such as from the introduction of a foreign agent such as serum, vaccine, antigenic substance or organism. "The boost of IgA/FcαR after challenge suggests IgG-mediated early control of infection and the potential contribution of IgA in both systemic and mucosal containment and, ultimately, elimination of the pathogen." (PMID 35977496, 2022). "Monoclonal as well as purified serum IgA antibodies showed MTB blocking activity independently of Fc alpha receptor expression, whereas IgG antibodies promoted the host cell infection." (PMID 27729388, 2016). "Within the CD14+CD16- classical monocyte compartment, expression of FcγRI increased significantly during the acute phase of DENV infection while the expression of FcγRIIa remained unchanged and the expression of FcαR was reduced relative to pre-infection levels." (PMID 37639455, 2023). "Upregulated genes in both infection and inflammation pathways were F2R, which links coagulation with inflammation; ADAR, crucial in antiviral immune responses; and FCAR, involved in IgA responses at mucosal sites." (PMID 41416938, 2025). "While monoclonal antibodies differ compared to polyclonal humoral immune responses in infection due to both antigen specificity and antibody glycosylation, these monoclonal studies suggest that IgA may mediate control of bacterial burden through both FcαR dependent and independent mechanisms." (PMID 31921122, 2019). "Fc receptors (FcαR, FcyR), Toll-like receptor TLR2 and cell surface receptor and differentiation marker CD14 were exclusively overproduced in the presence of hSAA-1 and downregulated (FcyR, TLR2, TLR4, CD14) during infection." (PMID 37781389, 2023). "More recently, it has been shown that in human FcαR (CD89) transgenic mice, intranasal administration of a human IgA1 mAb specific for Acr1 combined with recombinant mouse IFN-γ significantly reduced bacterial load after intranasal Mtb-infection." (PMID 33679802, 2021). "We show that IgG, but not IgA, mediated ADE of infection in cells expressing both FcαR and FcγRs." (PMID 37639455, 2023). "Indeed, when this experimental setup was expanded to the A549 human alveolar epithelial cell line expressing FcRn but not FcγRI, FcγRIII, FcγRII, or FcαR there was an enhancement of CFU noted upon infection with Mtb opsonized with monoclonal IgG isotype and inhibition with the IgA isotype." (PMID 31921122, 2019).
FCAR also shares sentences with these, for which no sentence is quoted: IgA nephropathy (11 papers); cancer (9); Arthritis (3); cardiovascular disease (2); HIV-1 infection (2); infectious disease (2); lymphoma (2); melanoma (2); alcoholic cirrhosis (1); Autoimmunity (1); B-cell lymphoma (1); bacterial infections (1); chronic myeloid leukemia (1); Cirrhosis (1); colitis (1); colorectal cancer (1); colorectal tumour (1); diabetes (1); glomerulonephritis (1); granulomatosis with polyangiitis (1); Hematuria (1); idiopathic cardiomyopathy (1); inflammation (1); influenza (1); kidney inflammation (1); metastatic disease (1); Myocardial fibrosis (1); myocardial infarction (1); pemphigus (1); pneumonia (1).
A further 10 diseases each share a sentence with FCAR in 1 paper.